IRF7 (interferon regulatory factor 7)
Diseases named in the same sentence as IRF7 in open-access papers (continued):
Sharing a sentence is not in itself a finding about the gene and the disease.
tumor (continued). "Restoration of BCL7A expression in cell culture impaired cell proliferation in competition cell growth assay and tumor formation on xenografts in vivo, altering the expression of genes like HMGCS1, H1-0, IRF7, which may help to explain its tumor suppressor role in AML." (PMID 36941700, 2023). "Those tumor-infiltrating pDCs are poor IFN-I producers, because of cytokine dysregulation by transforming growth factor β (TGF-β) and TNF-α secretions in the tumor microenvironment that inhibit the IFN-I secretion of pDCs through the inhibition of IRF-7 expression, and favors Treg expansion." (PMID 35884612, 2022). "In addition, IRF7 and SHC1 were hub IRGs in PPI network, and the vitro assays proved that they could promote tumor progression." (PMID 35692836, 2022). "In addition, IRF7 can upregulate the expression of anti-inflammatory genes such as IL10 and downregulate pro-inflammatory genes such as IL1B, TNF, CXCL1 and CXCL2 to polarize microglia to the M2 type, thereby establishing a tumor microenvironment that exerts immunosuppressive effects." (PMID 37251373, 2023). "Finally, MDSCs were shown to be upregulated in the absence of Irf7 in a tumor model." (PMID 34220829, 2021).
cancer (77 papers, 2009 to 2026). A tumor composed of atypical neoplastic, often pleomorphic cells that invade other tissues. "The dual role of IRF7 in modulating both protective and pathogenic inflammation aligns with its established functions in other chronic inflammatory diseases and cancers." (PMID 40016346, 2025). "Upregulated IRF7 gene in breast cancer elicits an immune response that is strongly associated with cancer cells decreased growth, nevertheless, also contributes to cell resistance to chemotherapy." (PMID 33922087, 2021). "Several ISGs, such as OAS family members and the tumor suppressors XAF1 and IRF7, have been shown to play crucial roles in counteracting cancer progression, and their increased expression is associated with the inhibition of cell growth and the promotion of the apoptosis of cancer cell lines." (PMID 28184177, 2017). "The cGAS/STING pathway serves as an upstream signaling hub for IRF7 activation and plays a key role in cancer and inflammatory diseases." (PMID 41164952, 2026). "Similar to the role of FHOD1 in cancer progression, IRF7 is critical in the development and metastasis of tumors." (PMID 41262249, 2025). "The resulting identification of FHOD1 and IRF7—two genes previously recognized for their roles in cancer pathogenesis—points to shared molecular pathways between oncogenesis and advanced atherogenesis." (PMID 41262249, 2025). "Four cancer-related hub genes (CRGs) were identified: Interferon Regulatory Factor 7 (IRF7), Formin Homology 2 Domain Containing 1 (FHOD1), Tumor Necrosis Factor (TNF), and Zinc Finger SWIM Domain Containing 3 (ZSWIM3)." (PMID 41262249, 2025). "Research lacks a thorough investigation of the impact of IRF7 on PAAD cancer cells and the differential expression of IRF7 in different PAAD cells." (PMID 39118300, 2024). "The activity of transcription factor interferon-regulatory factor 7 (IRF7) prominently regulates cancer dormancy due to its substantial role in the inhibition of natural killer (NK) and CD8+ T-lymphocytes." (PMID 36902406, 2023). "Firstly, two analysis databases including UALCAN and GEPIA were used, and the results revealed that as for MMP9 and IRF7 genes, they gain of expression in most of human cancers." (PMID 37438709, 2023). "IRF7 can also act as a pro-oncogene to inhibit the expression of microRNA regulators and apoptosis of cancer cells." (PMID 37251373, 2023). "In contrast, the overexpression of IRF7 was found only for the cancer cell line A539 and in dendritic cells." (PMID 36553678, 2022). "Analyzing protein expression levels in CRC and normal tissues with the HPA database revealed that IRF3 and IRF7 were upregulated in cancer tissues." (PMID 34488791, 2021). "Recent studies have also shown that the type I IFN system has control over cancer spread as depletion of IRF7 increases metastatic burden in mice and humans." (PMID 33621216, 2021). "Consistent with the present findings, BRG1 was found to suppress CDKN2A and IRF7 expression in GBM cancer stem cells." (PMID 33528916, 2021). "The network surrounding Il10ra shows that many of them are cancer related, e.g., Reg3g, Aoc1, Mep1a, Irf7, Gas6, B3gnt7, Tap1, Tgm2, and Nos2." (PMID 33396408, 2020). "Chemotherapy treatment activated IFN signaling in cancer cells through an autocrine and self-sustained increase in TF and interferon regulatory factor 7 (IRF7)." (PMID 32300189, 2020). "Upregulated IRF7 expression in treated cancer cells is responsible for reduced cell growth, suppressed mobilization of CD11b+Gr1+ MDSCs, increased expansion of DCs, T and B lymphocytes and chemoresistance." (PMID 30546090, 2019).
cancer (continued). "The observed increase (up to several thousand-fold over control cells) of dsRNA viral transcripts in the cytoplasm of the cancer cells activated innate PRRs, as well as transcription factor IRF-7, resulting in the induction and secretion of IFN-I/III." (PMID 28359286, 2017). "This strongly supports the contention that IRF7 is a target in LAM and other TSC-deficiency-related pathologies, such as TSC and cancer." (PMID 25476905, 2014). "From our analysis suggesting IRF7 to be a potentially important cancer-specific hypermethylation induced down-regulation event, we sought to create a list of functionally derived genes closely associated with its re-expression." (PMID 24162015, 2013). "The transcription factor IRF7 has been reported by others to be hypermethylated in cancer, as it is in our NSCLC line with the lowest basal expression." (PMID 24162015, 2013). "The research has significant implications for our understanding of OS pathogenesis and indicates that IRF7 might be a hopeful therapeutic target for OS treatment via interfering with cancer metabolic processes." (PMID 34975316, 2022). "Considering that interferon regulatory factor‐7 (IRF7) regulates the development of G‐MDSC through S100A9 gene transcription in cancer 19 and modulates progression of EAE in mice, we also compared relative expression of IRF7 mRNA in PBMC of MS patients before and after MPPT." (PMID 33094923, 2020). "Although activation of the IRF7/IFN-β/IFNAR pathway contributes to cancer cell resistance against chemotherapy, the fraction of cancer cells surviving chemotherapy is small (15% after 48 h and much less at later time points) in spite of rapid (i.e., within 24 h) activation of the pathway." (PMID 30546090, 2019). "Furthermore, when MAD5/MAVS/IRF7 axis is genetically inactivated, cancer cell lines become insensitive to 5-aza-2′-deoxycytidine treatment." (PMID 29706891, 2018). "Thus, induction of a viral mimicry state in cancer cells by 5-aza-2′-deoxycytidine is dependent on the activation of MAD5/MAVS/IRF7 axis and type III IFNs." (PMID 29706891, 2018). "However, the cases where TF and TPAC scores do have a consistent direction of association for a cancer type across all of the Hallmark gene sets, e.g, KLF13, THAP11 and IRF7 for GBM, are consistent with prior findings on TFs whose activity is linked to cancer (KLF13, THAP11, and IRF7)." (PMID 38206988, 2024). "Furthermore, the IRF7 protein may exert a direct influence on cancer cell gene expression and subsequent cell death via the extracellular vesicle pathway." (PMID 39118300, 2024). "Interestingly, IRF7 can also act as an oncogene that promotes cancer development." (PMID 37251373, 2023). "Seventy-four unique Reactome terms were selected in IStoI comparison, including “MAP2K and MAPK activation”, “TRAF6-mediated IRF7 activation”, “CTLA4-inhibitory signaling”, “signaling by Hippo” and “signaling by WNT in cancer”." (PMID 39000404, 2024). "Therefore, the role of IRF7 in cancer development may be different in various conditions." (PMID 37251373, 2023). "Transforming growth factor β (TGF-β) is abundant in these cancers and has been identified as the main soluble factor in the TME responsible for suppressing IFN-α secretion by TA-pDCs through inhibition of IRF7 signaling." (PMID 38239354, 2023). "IRF7 can also downregulate the expression of S100A9 and reduce the aggregation of G-MDSCs to limit the metastasis and spread of cancer cells." (PMID 37251373, 2023). "Further results noted were that miR-145-5p expressed genes mimic the gene expression of STAT1, a downregulation of IRF7 was noted in the GBC, and an activation of STAT1 was significantly noted in carcinoma cells of the gallbladder." (PMID 35035811, 2022). "The transfection of BNC2 to A549 cells led to the up-regulation of numerous ISGs, of which a subset (XAF1, IRF7, OAS family) is known to inhibit cancer growth and promote the apoptosis of cancer cells." (PMID 28184177, 2017).
cancer (continued). "By matching these basal gene expression and DNA methylation patterns, including that of a core interferon pathway transcription factor, IRF7 in the TCGA project, we extrapolate our in vitro AZA-induced gene signature to hundreds of primary NSCLC cancers." (PMID 24162015, 2013). "Moreover, IRF7 can stimulate the expression of MHC-II and elicit a phenomenon known as “immune cloaking”, through which a cancer cell can appear as a niche-resident immune cell." (PMID 36902406, 2023). "Transcription factor (TF) motifs, including CEBPB (+), FOSB (+), SAP30 (+) and ATF4 (+), were significantly upregulated in CNV high cancer cells, while IRF3 (+), ETV7 (+), STAT1 (+) and IRF7 (+) were downregulated, indicating promising new regulatory networks driven by TFs in OS cells." (PMID 36596773, 2023). "In addition, the IRF7 molecule (interferon regulatory factor 7, IRF7) is downstream of type I interferon signalling playing a pivotal role in initiating multiple anti-cancer immune responses." (PMID 36267973, 2022). "Increased levels of phosphorylated IRF3 but not IRF7 were detected after poly(I:C) electroporation in mammalian carcinomas." (PMID 35737804, 2022). "An overview of different strategies adopted to suppress these IRDS genes (for example; STAT1, IRF7, OAS family and BST2) in cancer inducing the sensitivity (chemo- and radiotherapy), as well as different ways by which the viruses inhibit the IRDS genes are addressed in this review." (PMID 33922087, 2021). "Furthermore, interferon regulatory factor 7 (IRF7) gene expression was upregulated in the presence of carnosine; IRF7 is known to decrease cancer growth and metastasis." (PMID 33809496, 2021). "We further assessed the relationship between IRF risk scores and immune and stromal scores in cancer patients to examine why increased IRF3 and IRF7 expression promotes immune cell recruitment without killing tumors." (PMID 34488791, 2021). "Gene ontology, molecular network and canonical pathway analysis of NASP overexpression demonstrated that the most significant changes were in proteins participating in organismal injury, immune response, and cellular growth and cancer pathways (major "hubs": TNF, FOS, EGR1, NFκB, IRF7, STAT1, IL6)." (PMID 19439102, 2009). "Interestingly, although IRF7 expression increased in many cell lines during acute interferon response activation by the cancer cells themselves, no significant changes were observed in patient samples." (PMID 39062738, 2024). "It deserves more investigations to study the regulatory mechanisms of IRF7 and the signaling pathways of the IRF system, which may become important targets for the treatment of infectious diseases, inflammation-related diseases or cancer." (PMID 37251373, 2023). "Lack of IRF7 expression corresponded to aberrant promoter hypermethylation of CpG islands within its promoter and was also identified as one of methylation-silenced genes in several cancer types including lung, hepatocellular, gastric and pancreatic cancers." (PMID 22194884, 2011). "The results demonstrated that the level of IRF7+ M1 polarised macrophages in normal tissues adjacent to cancer was markedly higher than in PAAD tissues, whereas the content of IRF7+ M2 polarised macrophages exhibited no alteration." (PMID 39118300, 2024). "Based on these considerations we propose that activation of the IRF7/IFN-β/IFNAR pathway contributes to the selection of cells resistance to chemotherapy (and eliciting an immune response) but is not sufficient to protect the bulk of the cancer cells initially exposed to chemotherapy." (PMID 30546090, 2019).
bacterial infection (17 papers, 2014 to 2025). "Then, interferon regulation factor (IRF)-7 plays an important role in the host defense against bacterial infection by regulating IFN-β." (PMID 38450161, 2024). "Bacterial infection significantly upregulated mRNA expression levels of Isg15, Mx1, Mx2, Irf-3, Irf-7, Tlr-2, Tnf-α, Cxcl-1, and Il-6 genes." (PMID 37929187, 2023). "Most relevant to the current review is the finding that reduction/inhibition of mucosal IRF7 expression with liposomal Irf7 siRNA resulted in protection of mice from bacterial infection and renal tissue damage." (PMID 30515152, 2018). "The requirement for activation of IRF3 and IRF7 in the IFN-β response to bacterial infection has been demonstrated in Listeria, C. pneumonia, and Neisseria meningitidis." (PMID 25798928, 2015). "However, transplantation of LPS-stimulated BMDMs restored bacterial infection, an effect which was alleviated by rFGF15 treatment but worsened by Irf7 overexpression." (PMID 40825908, 2025). "IRF7 plays an important role in the host defense against bacterial infection by regulating IFN-I." (PMID 37251373, 2023). "Our findings further elucidate the role of IRF7 in regulating ferroptosis by transcriptionally regulating ACSL4 expression, suggesting that IRF7 could be a promising therapeutic target to protect BMSCs from bacterial infections (as illustrated in the schematic diagram)." (PMID 39166412, 2024). "The results demonstrated that knockdown of IRF7 mitigated the death rate of BMSCs infected by S. aureus and E. coli, and a combined regimen of Fer‐1 and si‐Irf7 manifested pronounced synergistic anti‐ferroptosis effects in the context of both bacterial infections." (PMID 39166412, 2024). "AjCRFB5a functions in the host immune response to bacterial infection by activating antimicrobial peptide LEAP2, and it works as a positive regulator of host antiviral immune responses by activating IRF3 and IRF7-mediated type I IFN signaling pathways." (PMID 37835763, 2023). "With these findings in mind, IRF3 and IRF7 seem to exhibit opposing effects during UTI and balance each other in order to achieve an effective but limited innate immune response to bacterial infection." (PMID 35860746, 2022). "Our findings together showed that AjCRFB5a participates in the host immune response to bacterial infection by inducing antimicrobial peptides mediated by LEAP2 and favorably modulates host antiviral immune responses by activating IRF3 and IRF7-driven type I IFN signaling pathways." (PMID 37835763, 2023). "The therapeutic value of IRF7 inhibition has been demonstrated by the experiment that mice treated with IRF7 inhibitors were protected against bacterial infection without unwanted renal tissue damage." (PMID 36269754, 2022). "In light of the interaction between NEURL3 and IRF3 or IRF7, we thus hypothesize that NEURL3 can also affect inflammation through the regulation of interferon signaling during bacterial infection." (PMID 35792897, 2022). "In addition, a further 12 ISGs of 380 tested ISGs including STAT1, STAT2, JAK1, IRF9, IRF2, IRF7 are key elements of IFN signaling, and classical and well-known ISGs such as ISG15, PKR, MX1, IFIT1, PML, IFI27 play key roles in viral or bacterial infections." (PMID 30717477, 2019).
infectious disease (7 papers, 2016 to 2025). A disorder directly resulting from the presence and activity of a microbial, viral, or parasitic agent in humans. "First, IRF3 is constitutively expressed and serves as a prime initiator of type I IFNs, but IRF7 is activated in the late phase of infectious disease and acts as a master regulator to trigger the transcription of type I IFN genes and IFN-stimulated genes." (PMID 41212050, 2025). "Additionally, the disease/function networks that associated with AGE downregulated Casp1, Tlr3, Serp1, Irf1, Irf5, and Irf7 genes were involved in the antimicrobial response, inflammatory response, and infectious diseases." (PMID 27734935, 2016).
inflammation (4 papers, 2012 to 2023). Aberrant reaction of the microcirculation characterized by movement of fluid and leukocytes from the blood into extravascular tissues. "In a model of acute lung inflammation induced by diesel exhaust particles (DEPs), IRF7 was able to induce RAPTOR expression together with IRF3, promote mTORC1 activation and signal transduction, inhibit autophagy, and thus promoting lung injury induced by DEPs." (PMID 37251373, 2023). "Since pulmonary inflammation is linked to systemic inflammation and resultant adverse effects, such as cardiovascular dysfunction, Irf7 may not only contribute to lung inflammation but to these other effects as well." (PMID 22776377, 2012). "The immunomodulator OM-85 shows promise as a safe and effective preventative treatment for protection against airways inflammation triggered by a diverse range of stimuli, but has not been studied in the context of IRF7-associated immunophenotypic responses to virus/allergen coexposure." (PMID 34367159, 2021). "Notably, although acute lung inflammation requires IL-17, chronic inflammation is dependent on type 1 IFN and IRF7." (PMID 23557436, 2013).
neurodegenerative disease (3 papers, 2015 to 2019). A disorder of the central nervous system characterized by gradual and progressive loss of neural tissue and neurologic function. "Similarly, the RING domain has been shown to strongly interact with the Ubc9 E2 SUMO ligase and be fundamental for the SUMOylation process of KAP1 substrates such as the interferon regulatory factor 7 (IRF7) and the neurodegenerative disease driving proteins τ and α-synuclein." (PMID 31427381, 2019). "Thus, the down-regulation of STAT1, STAT2, IRF7 and IRF9 through GSK-J4 could inhibit neurodegenerative diseases as well as brain inflammation." (PMID 28747667, 2017). "Thus, the downregulation of Irf1, Irf7, and Irf9 through JQ1 could inhibit neurodegenerative diseases as well as brain inflammation." (PMID 25890327, 2015).
neurological disease (3 papers, 2018 to 2025). "Mice deficient in type I interferon receptors or key signaling molecules (IRF3, IRF7, or MAVS) develop neurologic disease following intraperitoneal infection, suggesting that innate immunity is likely responsible for controlling JCV in the periphery and preventing neuroinvasion." (PMID 41313001, 2025). "All weanling Irf3-/-xIrf7-/- DKO mice either died or developed neurological disease at 3 dpi for INKV, and at 5–6 dpi for JCV, indicating that signaling through IRF3 and/or IRF7 was critical for the protection of mice from neuroinvasive disease from JCV and INKV." (PMID 35245345, 2022).
connective tissue disorder (2 papers, 2015 to 2023). A disease involving the connective tissue. "We also find evidence for activation of multiple other inflammatory and connective tissue-disorder pathways mediated through pro-inflammatory TF genes such as STAT3, IRF1 and IRF7, CEBPB and SMAD4." (PMID 26202100, 2015).